HDAC1 (histone deacetylase 1)
Diseases named in the same sentence as HDAC1 in open-access papers (continued):
Sharing a sentence is not in itself a finding about the gene and the disease.
tumor (continued). "Moreover, treatment of HDAC1-silenced MDA-MB-231 tumor cells with vorinostat did not further increase CTL lysis relative to vehicle control." (PMID 26862729, 2016). "Taken together, these results indicate that reduction of Hdac2 in absence of Hdac1 (Hdac1Δ/Δ; Hdac2Δ/+) impacts Eμ-myc tumorigenesis by reducing the Eμ-myc-induced blasts in the BM, resulting in reduced circulating tumor cells and eventually delays Eμ-myc tumorigenesis." (PMID 27886239, 2016). "In addition to EMT regulation, the well-known property of miR-34a is its tumor suppressor function via inducing cell cycle arrest and apoptosis in various cancer types by targeting several molecules crucial for sustaining tumor growth such as CDK4/6, MET, HDAC1, E2F3 and Bcl-2." (PMID 25614041, 2015). "Our results show that the mRNA and protein levels of HDAC1 and HDAC2 were both decreased in the presence of wogonin, indicating that acetylated histone protein may promote expression of tumor suppressive proteins and thereby inhibit tumor progression." (PMID 24265759, 2013). "Indeed, we provide support for the notion that both HDACi and MTM promote neuroprotection by inhibiting the expression or functions of proteins that mediate transformation such as Myc, HDAC1, HDAC2 and HDAC3 and by promoting the expression of tumor suppressors such as p21waf1/cip1." (PMID 22582024, 2011). "Thus, HDAC-1 expression could be added to the list of potential markers of prolonged DFS and tumour aggressiveness." (PMID 16595007, 2006). "Given the high levels of HDAC1 in these cells and our hypotheses that epigenetic regulation is key in driving pediatric liver tumors, we asked if HDAC inhibition might enhance cisplatin efficacy to inhibit the proliferation of hbl cells and reduce tumor cluster formation." (PMID 39001363, 2024). "Similarly, inhibition of Gank as well as induction of C/EBPβ, HDAC1 proteins and other tumour suppressor proteins, through activation of FXR by CDCA and GW4064, inhibited liver carcinogenesis, while, FXR knockout mouse developed tumour with elevated Gank and decreased C/EBPβ levels." (PMID 35006466, 2021). "Inhibition of HDAC1 promoted acetylation of histone H3/H4 in IFN-β1 promoter, and enhanced phosphorylation of interferon regulatory factor (IRF) 3 and its binding to the IFN-β promoter, which could lead to an anti-tumor immune response of macrophages microenvironment." (PMID 34880761, 2021). "However, in PCa, the function of HDAC1 in tumor progression is not clear." (PMID 32546700, 2020). "The results of the present study revealed that the expression levels of HDAC1/2 were reduced at the mRNA and protein levels in the presence of AMP, indicating that acetylated histone proteins may promote the expression of tumor suppressive proteins and thus inhibit tumor progression." (PMID 25333250, 2015). "Thus, HDAC1 but not HDAC2 negatively controls tumour cell proliferation in the epidermis." (PMID 24240174, 2013). "Conversely, the expression of HDAC1 and HDAC2 increases with tumor progression and recurrence, with no significant changes in other antigens based on tumor grade." (PMID 40940748, 2025). "Molecular profiling revealed on-target effects of combined HDAC1/2 and PI3K/AKT inhibition independent of tumor phenotype." (PMID 37823778, 2023). "As an example, the synergistic regulation of histone deacetylase 1 (HDAC1) by OCT4, SOX2 and NANOG plays important roles not only in the development of ESCs but also in the growth of tumor cells." (PMID 25171496, 2014). "When the core is absent, YY1 recruits histone deacetylase 1(HDAC1) to repress the B23 gene, a gene which suppresses multiple tumor suppressors and, hence, exhibits oncogenic effects." (PMID 25053986, 2014).
tumor (continued). "HDAC1 (P=0.006) and HDAC2 (P=0.047) expression but not HDAC3 (P=0.584) expression correlated positively with Gleason scores, with high-grade tumours expressing both isoforms at higher rates." (PMID 18212746, 2008). "Additionally, in vivo, St.5 significantly reduced tumor growth (by 75%) in PC3 xenograft models without evident toxicity, highlighting it as a promising selective HDAC1 inhibitor for advanced prostate cancer therapy." (PMID 41440016, 2025). "Furthermore, two of our identified candidate biomarkers, HDAC1 and NARS, were found to have similar expression patterns in nPR(±) tumor tissues (data not shown)." (PMID 35971177, 2022). "However, the fascinating observation of our study is that the hub genes including CDK1, CDK2, CCNB1, and HDAC1 and common genes including E2F3 identified in Rb tissues are well-known oncogenes that trigger cell cycle progression in tumor cells in the absence of RB1 gene." (PMID 35359459, 2022). "However, our results on p300, HDAC1 and SIRT levels in non-tumor vs. tumor tissues (data not shown) could not explain enhanced APE1 acetylation in tumor cells." (PMID 27655688, 2016).
infection (44 papers, 2009 to 2026). The state of being infected such as from the introduction of a foreign agent such as serum, vaccine, antigenic substance or organism. "In a previous study, we had shown that infection of human macrophages with virulent M. tuberculosis causes the levels of histone deacetylase 1 (HDAC1) to increase significantly and repress expression of the IL-12B gene." (PMID 33627504, 2021). "Infection with Anaplasma phagocytophilum, an intracellular pathogen causing human granulocytic anaplasmosis, causes upregulation of HDAC1 leading to a globally increased HDAC activity." (PMID 32466312, 2020). "Analysis of proteins captured with pHDAC1gfp by mass spectrometry predicts that HDAC1 associates with a substantial number of cellular and viral proteins during infection." (PMID 20585571, 2010). "Together, these findings indicate that L. infantum-induced HDAC1 upregulation modulates the expression of key innate immune response genes, contributing to the establishment of infection in canine macrophages." (PMID 41940587, 2026). "Having uncovered that HDAC1 deletion resulted in a reduction of Texeff-like cells 30 days p.i., we next determined the time point during infection at which Texeff-like cell differentiation is affected by HDAC1 deficiency." (PMID 40464916, 2025). "Histone deacetylase genes (HDAC1 and HDAC8) had increased expression of L6 alleles, while small nuclear RNA genes (SNORA68 and SNORA72) expressed higher levels of L7 alleles with infection in T cell subsets." (PMID 39880866, 2025). "Upon infection, HDAC1-cKO mice displayed a similar degree of a transient weight loss over a period of 4 wk in comparison to WT mice." (PMID 40464916, 2025). "MiR-449b has been proven to be a regulator of histone deacetylase 1 and interferon beta in IAVs infection." (PMID 38178220, 2024). "The results showed that the RNA levels of FMDV increased in the cells after infection, while the expression of HDAC1 was suppressed." (PMID 37162335, 2023). "Compared with the control group, PCV2 infection significantly upregulated the expression levels of HAT1 mRNA and significantly downregulated the expression levels of HDAC1 mRNA in 3D4/2 cells at 8, 12, 24 or 36 h post-infection (p < 0.05 or p < 0.01)." (PMID 35624806, 2022). "In mice fed a western-type diet, AIEC infection decreases HDAC1 expression, inducing H3 hyperacetylation to favor their own colonization." (PMID 36175163, 2022). "Taken together, we suggest that intracellular parasites in an early phase of infection negatively regulates BRG1 by using host HDAC1 for its survival inside the host." (PMID 35433496, 2022). "We now show that after infection with M. tuberculosis, HDAC1 is phosphorylated, and the levels of phosphorylated HDAC1 (pHDAC1) increase significantly in macrophages." (PMID 33627504, 2021). "IMPORTANCE Following infection with M. tuberculosis, levels of HDAC1 go up in macrophages, and it is recruited to the promoter of IL-12B where it hypoacetylates histone H3, leading to the downregulation of the gene." (PMID 33627504, 2021). "Since Gc-HDAC has high 3D homology to human HDAC1 and peripheral monocytes express human HDAC1, we assessed the expression of both genes during infection of human peripheral monocytes." (PMID 32085531, 2020). "At 6 h post-infection, higher expression of HDAC1 protein (~ 1.5 fold) was observed compared to the levels observed in uninfected cells (UI)." (PMID 32275661, 2020). "The transcript levels of HDAC1 at 6 h post-infection was ~2.2-fold (P<0.0001) higher compared to the levels in the uninfected cells (UI)." (PMID 32275661, 2020). "At 6 h post-infection, HDAC1 occupancy at the defense genes promoters increased in 9 out of 10 genes studied." (PMID 32275661, 2020). "Together with its strong upregulation upon infection, this supports an important role for HDAC1 during infection with Mtb." (PMID 32117228, 2020).
infection (continued). "Since we observed an increased occupancy of HDAC1 at promoter regions of defense genes at 6 h post-infection, we then decided to check the HDAC1 enzyme activity and expression in the infected THP-1 cells." (PMID 32275661, 2020). "A decrease in HDAC1 expression was observed at 12 and 24 h post-infection in comparison to the values obtained at 6 h post-infection." (PMID 32275661, 2020). "Our data indicate that Leishmania infection results in increased expression of HDAC1 at 6 h post-infection both at the transcriptional and translational levels." (PMID 32275661, 2020). "A decrease in HDAC1 levels was observed at 12 and 24 h post-infection in comparison to the values obtained at 6 h post-infection." (PMID 32275661, 2020). "HDAC1 occupancy at the promoters of the defense genes significantly increased upon infection, which in turn resulted in decreased histone H3 acetylation in infected cells, resulting in the down-regulation of mRNA expression of host defense genes." (PMID 32275661, 2020). "We observed a significant increase in HDAC1 activity at 6 h post-infection when compared to the HDAC1 activity in uninfected THP1 cells (P = 0.00001)." (PMID 32275661, 2020). "An increase in the transcript, protein levels and activity of host HDAC1 was observed at 6 h post-infection." (PMID 32275661, 2020). "Histone deacetylase 1 (HDAC1) transcript levels, protein expression, and enzyme activity showed a significant increase upon infection." (PMID 32275661, 2020). "We found that HDAC1 knockdown in HIV-1-infected cells decreased levels of late reverse transcripts early in infection." (PMID 31744547, 2019). "It was characterized to bind host DNA and nuclear proteins in 2004, and in 2009 it was shown to be the factor responsible for silencing granulocyte respiratory burst by recruiting histone deacetylase 1 (HDAC1) to alter granulocyte function with infection." (PMID 27703927, 2016). "Infection of adeno-MDM2 (Ad-MDM2) reduced exogenous HDAC1 protein expression by Ad-HDAC1 in a dose-dependent manner in RVSMCs." (PMID 26832969, 2016). "How HDAC1 is recruited to the promoter of these genes during infection, however, requires further investigation." (PMID 26697414, 2015). "Here we report that infection of macrophages by live virulent MTB induces upregulation of HDAC1 expression which in turn is effectively employed to deacetylate histone H3 at the promoter of IL-12B gene." (PMID 26697414, 2015). "This indicated that the increase in HDAC1 levels upon infection with live MTB H37Rv corroborated well with a concomitant decrease in histone H3 acetylation." (PMID 26697414, 2015). "In this study we observed that 24 h after infection, there was a dramatic upregulation of HDAC1, and a concomitant decrease in the levels of acetylation of histone H3 in macrophages infected with live virulent MTB H37Rv." (PMID 26697414, 2015). "Results demonstrated that the expression levels of Apaf-1, Bax, Bim, and PUMA were increased after infection with OV.HDAC1, OV.p73, as well as OV.shHDAC1.p73 compared to the parental OV.Luc." (PMID 25071017, 2014). "Intriguingly, the redistribution of these complex members appears to be temporally regulated, with HDAC1/CoREST accumulating in the cytoplasm at four hours post-infection (hpi) and LSD1 changing localization at 8 hpi." (PMID 23807710, 2013). "In contrast, when the average centrosome distance decreased, as it did in HDAC1-depleted cells, the efficiency of acidification and infection increased." (PMID 22046129, 2011). "The results observed after HDAC1 depletion seemed to support a correlation between centrosome architecture and infection." (PMID 22046129, 2011). "That HDAC8 and HDAC1 had opposing effects on centrosome distance and infection was further supported by double transfection experiments where the two were silenced simultaneously." (PMID 22046129, 2011). "From these results, we conclude that pUL29/28 is necessary for the interaction between pUL38 and HDAC1 during infection." (PMID 20585571, 2010).
infection (continued). "HDAC1 overexpression enhanced infection, whereas pharmacologic and siRNA HDAC1 inhibition significantly decreased bacterial load." (PMID 19543390, 2009). "Gene expression analysis of HDAC1 and HDAC2 in A. phagocytophilum-infected cells by qRT-PCR showed a transient increase in HDAC1 expression that peaked within 24 hours post-infection, whereas HDAC2 transcription steadily increased over time." (PMID 19543390, 2009). "However, alanine aminotransferase levels were reduced in the serum of HDAC1-cKO mice at day 30 post infection (p.i.), and aspartate aminotransferase levels showed a similar tendency." (PMID 40464916, 2025). "Such visualization at later infection timepoints could have skewed the results and the effect of HDAC1 and HDAC2 on IAV-induced STAT3 nuclear translocation." (PMID 39861822, 2024). "Further, silencing of HDAC1 resulted in the reversion of CIITA expression indicating that histone H3 deacetylation is an important player in establishing parasite within the host cell at an early stage of infection." (PMID 35433496, 2022). "HDAC1 was substantially upregulated 24 h post-infection in both Mφ1 and Mφ2." (PMID 32117228, 2020). "HDAC1 activity at 24 h post-infection was down to basal levels as in the uninfected THP1 cells." (PMID 32275661, 2020). "HDAC1 expression and activity were found to be dependent upon the stage of infection." (PMID 32275661, 2020). "The transcript levels of HDAC1 were quantitated by qRT-PCR at 6 h post-infection and NaB treatment." (PMID 32275661, 2020). "This showed that HDAC4 was down-regulated during infection, while HDAC1 remained stable." (PMID 31127039, 2019). "Interestingly, PA infection of WT mouse lung inhibited HDAC1/2 activity, and enhanced H3 and H4 histone acetylation, however, genetic deletion of Sphk2 in mice attenuated PA mediated H3 and H4 histone acetylation." (PMID 31842752, 2019). "In addition, the TLR3 and IL6 mRNA levels were increased in HDAC1-depleted cells infection with IAV." (PMID 29312300, 2017). "Knockdown of HDAC1 depressed the infection through activation TBK1-IRF3 pathway." (PMID 29312300, 2017). "HDAC1 and NF-κB signaling coordinate to repress inflammatory genes during infection." (PMID 28713342, 2017). "Here we demonstrated that the levels of HDAC1 protein in the macrophages indeed increase after infection with live, virulent MTB whereas they decrease in macrophages infected with live, non-virulent MTB H37Ra, and even in those treated with heat-killed MTB H37Rv or LPS." (PMID 26697414, 2015). "As expected, knockdown of HDAC1 significantly increased the levels of IL-12B expression in macrophages infected with live MTB, thus confirming the observation that downregulation of IL-12p40 upon infection with live MTB was indeed a result of infection-induced HDAC1 expression." (PMID 26697414, 2015). "In the absence of infection, phosphorylation is an established regulator of HDAC1 and HDAC2 activity and protein associations." (PMID 23807710, 2013). "Upon infection, components of the HDAC1/CoREST/LSD1 complex are observed to translocate to the cytoplasm, indicating that this complex or its members may adopt new functions in response to viral infection." (PMID 23807710, 2013). "Increased promoter recruitment of p50, HDAC1, HDAC2 and Sirt1 to the NF-kB-associated site A region of the mir-424-503 gene was found in cells following infection, as assessed by ChIP analysis using primers covering the NF-kB-binding region within the promoter." (PMID 23724129, 2013). "In this study, we focused on class I HDACs (HDAC1, 2, 3, 8) and their role in infection." (PMID 22046129, 2011). "When HDAC1 was depleted, infection by IAV more than doubled." (PMID 22046129, 2011). "HDAC1 depletion reduced the splitting of centrosomes, and enhanced infection." (PMID 22046129, 2011). "In HeLa ATCC cells, HDAC1, 3, and 8 silencing had similar effects on infection as in A549 cells." (PMID 22046129, 2011).